INS (insulin)
Diseases named in the same sentence as INS in open-access papers (continued):
Sharing a sentence is not in itself a finding about the gene and the disease.
Insulin resistance (continued). "Mice fed with a HFD presented a significant increase of leptin, and insulin concentrations, accompanied by a notable increase in HOMA-IR than the control, which were the hallmark features of leptin, and insulin resistance as well as metabolic disorders." (PMID 36558373, 2022). "Obesity-induced insulin resistance results in abnormal elevated circulating insulin, promotion of fatty acid synthesis, and increase in FGF21 ultimately causing a FGF21-resistant state." (PMID 36499655, 2022). "• Increase insulin resistance through TGFβ/Smad3 signaling via the repression of the insulin promoter and suppression of insulin level and secretion. • Inhibition of adipocyte differentiation. • Correlation with high levels of serum glucose." (PMID 35422689, 2022). "By the activation of 5-adenosine monophosphate kinase (AMPK), it improves insulin sensitivity in individuals with insulin resistance and increases the translocation of the glucose-4 transporter into the plasma." (PMID 35209140, 2022). "Considering that the process of lipid production is inhibited by insulin, patients with insulin resistance showed higher lipid levels especially those with severe forms of OSA." (PMID 35694268, 2022). "Insulin resistance is accelerated by obesity accompanied by accumulation of dysfunctional adipose tissues, followed by a compensatory increase in insulin secretion." (PMID 35432205, 2022). "Type 2 diabetes (T2D) is a highly prevalent, multifactorial disorder with a complex etiology that debuts when pancreatic β-cells fail to produce enough insulin to compensate for insulin resistance." (PMID 36611962, 2022). "Several studies show that sDPP4 levels are associated with the presence of insulin resistance in both animal models and humans, and experimental data point towards a role of DPP4 as a proper mediator, and not only a biomarker, of impaired insulin sensitivity." (PMID 36140405, 2022). "The antidiabetic activity of these plants is thought to be mediated via various mechanisms, including stimulating insulin secretion from pancreatic B cells, increasing insulin binding to receptors, reducing insulin resistance, and improving glucose tolerance." (PMID 36601006, 2022). "About biomarkers, we checked TG, LDL-C, HDL-C, blood insulin, pre-prandial blood sugar, and the Homeostasis Model Assessment-Insulin Resistance index (HOMA-IR)." (PMID 36249262, 2022). "Protein tyrosine phosphatase 1B (PTP1B) functions as a negative regulator and is therefore considered as one of the key protein targets modulating insulin signaling and insulin resistance." (PMID 35408611, 2022). "One of our patients had severe hypertriglyceridemia (1007 mg/dl), elevated insulin level (76.4 μIU/ml) and insulin resistance (HOMA‐IR: 38.8)." (PMID 36101829, 2022). "Homeostasis model assessment–estimated insulin resistance (HOMA-IR) was measured from fasting plasma insulin and glucose collected at baseline, as a measure of insulin resistance." (PMID 36364884, 2022). "Noteworthy, RRAD coding Ras-related GTP-binding proteins was shown in the past to contribute to glucose uptake reduction in response to insulin, thus, leading to insulin resistance." (PMID 36091019, 2022). "Elevated blood levels of NEFA are also strongly associated with insulin resistance and type 2 diabetes, whereas lowering of NEFA exerts an opposite effect and improves tissue insulin sensitivity." (PMID 36014488, 2022). "JNK can directly induce insulin resistance through a phosphorylated IR substrate (IRS) 1, inhibiting insulin cascades and potentially increasing the risk for AD." (PMID 35128745, 2022). "Recently, we have shown that phosphorylation status of fetuin-A is critical for inhibition of insulin action, correlating with obesity and insulin resistance." (PMID 35522655, 2022). "The cross-talk between adipocytes and macrophages accumulated in adipose also led to insulin resistance by blunting insulin action." (PMID 35860700, 2022).
Insulin resistance (continued). "Inherent insulin resistance in PCOS is attributed to inappropriate reaction to insulin in metabolically active marginal tissues including adipose tissue and skeletal muscle." (PMID 36407241, 2022). "It is possible that participants experienced insulin resistance and produced more insulin to maintain glucose concentration at fasting levels, with no manifest impairment to glucose concentration." (PMID 36146310, 2022). "In the past decades, plasma insulin has been established as a clinical biomarker of insulin resistance." (PMID 35887628, 2022). "Insulin resistance is defined as insulin receptor damage and the disruption of insulin action, where insulin unable to take up the glucose into the cell, resulting in a hyperglycemia." (PMID 35487948, 2022). "More specifically, PTPs such as PTPN1, PTPN2, PTPN9, PTPN11, PTPRF, and DUSP9 are associated with the pathogenesis of type 2 diabetes, as they negatively modulate insulin signaling and induce insulin resistance." (PMID 35409287, 2022). "The most commonly used methods to assess insulin resistance are indirect ones, consisting in the determination of fasting glucose and insulin concentrations, or in performing the oral glucose tolerance test." (PMID 36613051, 2022). "A biphasic relation between insulin resistance and change in BMD is plausible; experimental data show that insulin has anabolic or catabolic actions on bone under different conditions and that bone itself can be an end-organ site of insulin resistance." (PMID 36278482, 2022). "To investigate the molecular mechanisms of hyperinsulinemia‐induced insulin resistance, we conducted well powered RNA sequencing (RNA‐seq) on cells exposed to prolonged insulin and serum starvation." (PMID 34921686, 2022). "LTB4 in turn increases glucose output from hepatocytes and impairs insulin-dependent Akt phosphorylation and abrogates the insulin-dependent inhibition of glucagon-stimulated glucose formation thereby contributing to insulin resistance and hyperglycemia." (PMID 35955975, 2022). "A large amount of IL-6 in a high-glucose environment can reduce insulin sensitivity, and excessive TNF-α will cause an increase in the free fatty acid content, which will eventually lead to insulin resistance." (PMID 35327635, 2022). "Here, we show that SGLT2i treatment improves hepatic insulin resistance, increases hepatic insulin clearance, and improves liver function in Japanese people." (PMID 35115614, 2022). "Hepatic insulin resistance reveals the failure of insulin to inhibit glycogenolysis and gluconeogenesis in the liver to maintain normal plasma glucose levels." (PMID 35743160, 2022). "The consequent positive effect against insulin resistance and obesity suggested a potential relationship with amelioration of local insulin sensitivity in obese subjects." (PMID 35204677, 2022). "Overall, 40% of the patients were overweight and 40% had insulin resistance, measured by fasting glucose and insulin concentrations." (PMID 36358604, 2022). "Additional investigations have demonstrated that BCAAs elevate insulin action and signaling procedures, while others have reported that they get worse insulin resistance in individuals with T1D1." (PMID 35589736, 2022). "The aim of the present study was to determine the role of individual PHLPP isoforms in insulin signaling and insulin resistance in neuronal cells." (PMID 36376971, 2022). "The disturbances in metabolic pathways are attributed to defects in insulin secretion due to the dysfunction of β-cells or insulin resistance or a combination of insulin resistance and β-cell dysfunction." (PMID 36042748, 2022). "In a study of 56 patients with T2D and coronary heart disease, resveratrol increased insulin sensitivity while decreasing insulin levels and insulin resistance compared with placebo controls." (PMID 36632095, 2022).
Insulin resistance (continued). "Smoking stimulates the secretion of Se and thus increases the level of insulin, which results in progressive failure of pancreatic β-cell function in the presence of chronic insulin resistance." (PMID 36235626, 2022). "Under insulin resistance conditions, the insulin-mediated suppression of glucose production by the hepatocytes and uptake of glucose by the skeletal muscles is impaired." (PMID 36430743, 2022). "GLUT4 is sensitive to insulin, and researchers found oryzanol attenuates insulin resistance by increasing GLUT4 expression in skeletal muscle." (PMID 35806430, 2022). "Hyperglycemia due to insulin resistance is characterized by hyperinsulinemia as the pancreatic beta cells are still functional, but attempt to overcome hyperglycemia by increasing insulin secretion." (PMID 35318939, 2022). "Previous studies have shown that circadian rhythm disorders destroy insulin sensitivity, leading to insulin resistance and obesity." (PMID 36590199, 2022). "Non-insulin-based insulin resistance index can predict AS due to a strong positive correlation with PWV." (PMID 36012003, 2022). "A previous study showed that high levels of NEFA induced insulin resistance by suppressing insulin signaling in hepatocytes." (PMID 35448496, 2022). "Liver steatosis causes the accumulation of lipids in hepatocytes and impairs insulin signaling, and it worsens insulin resistance by stimulating gluconeogenesis." (PMID 35315984, 2022). "Mice had elevated levels of plasma leptin and insulin and increased Homeostatic Model Assessment for Insulin Resistance (HOMA-IR) indicators of insulin resistance." (PMID 35910891, 2022). "High-fat treatment resulted in insulin resistance characterized by an impaired insulin signaling pathway." (PMID 35806430, 2022). "The progressive impairment of insulin sensitivity results in insulin resistance, defined as an increased insulin requirement to maintain glucose homeostasis." (PMID 36365189, 2022). "Elevated mannose, a C2 epimer of glucose, has been associated with incident type 2 diabetes (T2DM) and CVD, and has recently emerged as a novel, insulin-regulated, biomarker of insulin resistance." (PMID 36151569, 2022). "Insulin sensitivity was assessed using Homeostatic Model Assessment of Insulin Resistance and the Matsuda Insulin Sensitivity Index." (PMID 35167495, 2022). "Even if the body weight was similar between adipose tissue-VEGF-D-overexpressed mice and littermate controls, enhanced lymphangiogenesis in adipose tissue increased insulin sensitivity and reduced insulin resistance compared to the controls." (PMID 35252405, 2022). "Downregulation of ACE2 by the entry of the virus can contribute to insulin resistance and insufficient insulin secretion through the RAS." (PMID 35336774, 2022). "The contribution of oxidative stress to insulin resistance is supported by data showing that treating high fat fed mice with a mitochondrial-specific antioxidant preserves insulin sensitivity." (PMID 35277006, 2022). "Insulin levels and insulin resistance, calculated from fasting glucose and insulin using the homeostatic model, decreased at WK2 and stayed lower at WK4 and WK6 in all groups (p < 0.001)." (PMID 36138878, 2022). "Anti-inflammatory drugs have been shown to improve insulin secretion, insulin resistance, and blood glucose levels in clinical intervention studies." (PMID 36145139, 2022). "Possible mechanisms include hyperinsulinemia in PC, PC-induced insulin resistance, impaired β-cell, and impaired insulin secretion." (PMID 35432196, 2022). "Cafeteria diet feeding was conducted with normal and diabetic animals to assess changes in insulin-mediated glucose metabolism and to investigate the effects of insulin resistance on the development of DIT." (PMID 36012714, 2022). "The mechanism of insulin resistance presents an enigma because retinol delivery provides a substrate for RA biosynthesis, an anti-insulin autacoid." (PMID 35458115, 2022).
Insulin resistance (continued). "Myostatin has also been shown to play a role in insulin resistance as it inversely correlates with insulin sensitivity in healthy adults." (PMID 35922829, 2022). "Soy consumption significantly lowered FPG, HbA1c, plasma insulin levels, insulin-resistance, TC, and LDL-C." (PMID 35425791, 2022). "The actual understanding of insulin resistance can be explained by the requirement of excessive insulin for the metabolic activities, while, besides metabolic activities, insulin is also required for mitogenic and reproductive actions." (PMID 35356614, 2022). "The reported wide range in blood glucose and insulin doses suggests that individual patient factors, such as co-existing insulin resistance, can influence the preferred treatment strategy during pregnancy." (PMID 35627517, 2022). "A murine model of insulin resistance evidenced the capability of TO for controlling diabetic dyslipidemia, impaired glucose tolerance, insulin resistance, and insulin sensitivity indices, and altered plasma glucose and insulin levels." (PMID 36014301, 2022). "While patients with IRAb classically have TBIRS presenting with severe insulin resistance and hyperglycaemia requiring high doses of insulin therapy, more than 10% of patients with IRAb present with autoimmune hypoglycaemia alone." (PMID 36387920, 2022). "The key to the physiopathology of hepatic fat accumulation is insulin resistance, a condition that is characterized by poor tissue response to insulin." (PMID 35920204, 2022). "Insulin resistance and subsequent hyperinsulinemia add a dysfunction of the insulin effect to suppress the hepatic glucose production; this through glycogen degradation (glycogenolysis) or de novo synthesis of glucose (gluconeogenesis)." (PMID 36233611, 2022). "The progression of T2DM occurs due to insulin resistance or the impaired secretion of insulin, and the impaired metabolism of proteins, lipids, and carbohydrates." (PMID 36355096, 2022). "Some data also reveal the metabolic profile of neurogenerative diseases, showing that patients present systemic insulin resistance and reduced insulin levels in the brain." (PMID 35408987, 2022). "The first stage is the transition from a healthy metabolism to a state of declining insulin action on peripheral tissues (insulin resistance) and prediabetes." (PMID 36160451, 2022). "Some insulin resistance was evident in preterm pigs during the first 4–5 days of life as indicated by the higher insulin secretory response after IAGTT." (PMID 35989990, 2022). "This latter finding is of high importance, as it demonstrates that high insulin levels can drive insulin resistance independently of HFD feeding, obesity, and hyperglycemia." (PMID 34823065, 2022). "The disease is characterized as multisystemic dysfunctions attributed to hyperglycemia resulting directly from insulin resistance (IR), inadequate insulin secretion, or enormous glucagon secretion." (PMID 35454311, 2022). "Herein, we showed that ageing promoted insulin resistance that is accompanied by increased insulin secretion." (PMID 35600301, 2022). "We for the first time reported detailed review on the mechanism, pathophysiology, and treatment interventions for the insulin resistance and hypersecretion of insulin." (PMID 35356614, 2022). "East Asian and American show different pathophysiology of T2DM, East Asian shows insulin resistance with mild obesity and low insulin secretion ability." (PMID 35672759, 2022). "Metformin, as an oral insulin-sensitizing agent, is widely used in the treatment of patients with type II diabetes, insulin resistance, metabolic syndrome and polycystic ovary syndrome." (PMID 35123389, 2022). "Smoking can also increase insulin resistance which makes the patients require more insulin for the control of their sugar level." (PMID 36289697, 2022).
Insulin resistance (continued). "Increasing insulin resistance due to aging, obesity, inflammation, and oxidative stress elevates insulin secretion, eventually leading to chronic hyperglycemia and decreased lifespan." (PMID 35159148, 2022). "Whereas HOMA-IR and disposition index, evaluate hepatic insulin resistance more than peripheral insulin sensitivity which was our target." (PMID 35631177, 2022). "Increasing levels of chronic subclinical inflammatory markers, such as C-reactive protein (CRP) and interleukin-6 (IL-6), are thought to be involved in the development of T2DM via insulin resistance onset and insulin secretion disruption." (PMID 35682821, 2022). "In contrast, HDL cholesterol improves insulin resistance by inhibiting β-cell apoptosis, promoting insulin secretion, and inhibiting the action of LDL cholesterol." (PMID 35992095, 2022). "Lipid-induced myocellular insulin resistance is likely more pronounced with palmitate than with oleate and is associated with PKC isoforms activation and inhibitory insulin signalling." (PMID 34704121, 2022). "Insulin resistance, hyperinsulinemia, and the anabolic effects on adrenal gland tissue, which have insulin and insulin-like growth factor-1 receptors, offer possible pathophysiological links." (PMID 35457158, 2022). "Insulin resistance, a pathological response to insulin hormone in insulin-dependent cells, is characterized by the presence of high glucose and insulin concentrations." (PMID 36313112, 2022). "The mutation of tau is also known to induce insulin resistance by increasing pSer-IRS1 and to cause insulin accumulation as oligomers." (PMID 36547082, 2022). "ROS production can activate the phosphorylation of IRS proteins and impair insulin signaling, directly related to mitochondrial dysfunction and insulin resistance." (PMID 36465171, 2022). "Recently, brain insulin resistance has been posited to lie at the cross-roads of many cognitive and metabolic disorders, and disruption of central insulin action has emerged as a plausible contributor to AP-induced metabolic dysfunction." (PMID 36441736, 2022). "They showed that RBP4 affects macrophages, dendritic cells, and CD4+ T-cells in adipose tissue, thereby promoting an inflammatory response, impairing insulin signaling and eventually leading to insulin resistance." (PMID 35334893, 2022). "Males showed induced insulin resistance and reduced insulin signaling pathway activity with moHF, in VAT and SAT respectively." (PMID 34997206, 2022). "Both studies stated that insulin signaling was impaired in transformed cells demonstrating the central role of tumor-induced insulin resistance in cachexia." (PMID 36091180, 2022). "Rosiglitazone (Avandia) and pioglitazone (Actos) belong to the class of thiazolidinediones (TZDs) drugs that act by increasing insulin sensitivity and are widely used for treating diabetic patients with insulin resistance." (PMID 36523368, 2022). "And NAFLD also contributes to insulin resistance by combined mechanisms such as increasing lipid metabolites including ceramides and diacylglycerols which inhibit insulin signaling." (PMID 36438727, 2022). "Glucoregulation was significantly improved according to glucose and insulin responses, homeostatic model assessment of insulin resistance indices and postprandial insulin sensitivity indices (p < 0.05)." (PMID 36430066, 2022). "Muscle insulin resistance reveals a suboptimal muscle glucose uptake response to normal insulin levels." (PMID 35547584, 2022). "Like most forms of non-autoimmune diabetes, GDM is thought to result from a combination of insulin resistance and inadequate insulin secretion to compensate for the degree of insulin resistance." (PMID 36432476, 2022). "Meanwhile, the glucose tolerance and insulin tolerance assay revealed that mice exhibited abnormal glucose tolerance and insulin resistance when animals were fed with HFD for 12 weeks." (PMID 35269401, 2022).